HSPB1 (heat shock protein family B (small) member 1)
Diseases named in the same sentence as HSPB1 in open-access papers (continued):
Sharing a sentence is not in itself a finding about the gene and the disease.
tumor (continued). "Taken together, our quantitative proteomic analysis detected the molecular triad, NPM1, GRP78 and RKIP participating together with NCL and HSP27/HSPB1 in a network related to tumor progression." (PMID 26108672, 2015). "Of interest, high levels of HspB1 cell surface expression were found to correlate with tumor growth and cell ability to metastasize." (PMID 24514166, 2014). "Taken together, our data suggest that MMP9-induced HSPB1 cleavage acts to regulate the activity of -tumor vascular ECs, releasing anti-angiogenic C-terminal fragment against tumor progression." (PMID 24465581, 2014). "Exogenous administration of HSPB1 inhibited the migration of HOS tumor cells through HUVECs, while HSPB1-neutralizing antibodies that trapped soluble HSPB1 increased tumor cell transendothelial migration." (PMID 24465581, 2014). "It has been previously shown that MMP9 is upregulated in tumor metastases and HSPB1 secretion is increased in tumorigenesis." (PMID 24465581, 2014). "Taken together, our data suggest that soluble HSPB1 inhibits VEGF function and that cleavage of soluble HSPB1 is increased as a host defense mechanism against tumor angiogenesis." (PMID 24465581, 2014). "To investigate the effect of soluble HSPB1 on tumor progression, we performed tumor cell transendothelial migration assays." (PMID 24465581, 2014). "By decreasing HspB1 level the proteasome activity is back to normal as well as the CD8+ T-cell-mediated tumor killing and the memory responses." (PMID 24514166, 2014). "A recent study performed in colorectal adenomas also suggests a possible role of HspB1 in overcoming PI3K/AKT induced OIS in tumours." (PMID 24514166, 2014). "HspB1 is also deeply involved in the invasion of tumor cells into surrounding tissues and formation of metastatic colonies." (PMID 24514166, 2014). "In this study, we demonstrate that HSPB1 processing by MMP9 releases anti-angiogenic fragments of HSPB1 and this cleavage acts to maintain the angiogenic balance in tumor progression." (PMID 24465581, 2014). "In transformed and tumour-derived cell lines we and others have shown that siRNA-mediated knockdown of hspB1 protein inhibited inflammatory gene expression by diminishing upstream pro-inflammatory signalling." (PMID 24143227, 2013). "Many studies have tried to decipher the mechanism that allow HspB1 to trigger tumor progression and metastasis." (PMID 24278676, 2012). "Previous studies clearly demonstrated that the high expression of human HspB1 in tumors correlates with increased tumor growth and enhanced metastatic potential." (PMID 22452810, 2012). "Notably, HSPB1 overexpression has been confirmed to inhibit erastin‐induced ferroptosis, thereby promoting tumor development and metastasis." (PMID 41454619, 2026). "Targeting Alkbh5/Hspb1/ferroptosis axis may enhance anti-tumor effects in combination therapy, highlighting a potential therapeutic approach for HCC." (PMID 41413253, 2025). "Notably, the upregulation of several of these genes, particularly NCF1, HSPB1, PIGT, and PTX3, was associated with poor prognosis, supporting the idea that these genes play a pivotal role in tumor progression and patient survival." (PMID 40656950, 2025). "In T_EP, there was significant upregulation of genes associated with malignancy, such as EPCAM, HSPB1, CEACAM6, MUC1, and LY6E, implicating their roles in tumor initiation." (PMID 40786043, 2025). "Finally, our in vivo studies showed that exosome administration promote tumour growth in nude mice of xenotransplantation, which was able to be eliminated by knockdown of HSPB1." (PMID 38682349, 2024). "HSPB1 overexpression led to increased tumor volume and tumor weight." (PMID 37454220, 2023).
tumor (continued). "In comparison, Fer-1 treatment group disrupted the survival benefit originating from circRNF10 knockdown, while the upregulation of ZBTB48 or HSPB1 completely abrogated the tumor suppressor effect mediated by circRNF10 knockdown, significantly reducing the survival time of mice." (PMID 37723588, 2023). "HSPB1 was significantly highly expressed in most tumours compared to normal tissues." (PMID 37241117, 2023). "Significantly, the tumors in the doxorubicin-injected mice bearing HSPB1-overexpressing cells were significantly larger and heavier compared to those in doxorubicin-injected mice implanted with control cells, suggesting that overexpression of HSPB1 attenuated the anti-tumor effect of doxorubicin." (PMID 37454220, 2023). "HSPB1 is widely expressed in various tumors and may contribute to tumor proliferation, migration, and drug resistance." (PMID 37268925, 2023). "HSPB1 was highly expressed in tumor tissues correlating with poor prognosis in CRC." (PMID 37377935, 2023). "The evidence showed a potential ferroptosis-inducing therapy strategy that ipatasertib could inhibit HSPB1 phosphorylation, enhancing erastin-induced ferroptosis, and thus killing tumor cells." (PMID 37158834, 2023). "Furthermore, the results of immunohistochemistry suggested that eIF5A was significantly reduced (g), and the ferroptosis marker proteins (FANCD2, SLC7A11, and HSPb1) were significantly downregulated in the tumor tissues of sh-eIF5A group mice (h)." (PMID 35874632, 2022). "At present, many studies have confirmed that HSPB1 is closely related to tumor." (PMID 35150481, 2022). "Mechanistically, a large number of biomolecules and tumor-associated signaling pathways, including DECR1, PANX2, HSPB1, ACOT8, SUV39H1, NCOA4, PI3K-AKT-mTOR signaling, VHL/HIF-2α pathway, and Hippo/TAZ signaling pathway, have been reported to regulate ferroptosis in urologic cancers." (PMID 34922551, 2021). "HSPB1 can negatively regulate the ferroptotic death of tumour cells." (PMID 33611848, 2021). "HspB1 mRNA and protein levels were lower in tumor tissue in a small study of thyroid carcinomas." (PMID 32927696, 2020). "HspB1 has been reported to be induced during tumor angiogenesis." (PMID 32927696, 2020). "HspB1 can enhance or inhibit cell proliferation and growth and tumor development." (PMID 32927696, 2020). "Then, UBC modulated STAT5A and HSF1 in the WNT and the MAPK signaling pathways to inhibit DNA repair through the mediation of HIST2H2BE and to induce antiapoptosis through the mediation of HSPB1, which might finally facilitate tumor growth." (PMID 30344796, 2018). "One can cite quercitin, berberin derivatives (EPO Patent 0813872-A1), paclitaxel, KNK437 and interferon-γ which suppresses HspB1 basal transcription and promoter activity thus enhancing hyperthermia-induced tumor cell death in vitro and tumor suppression in vivo." (PMID 24514166, 2014). "In spite of the fact that the molecular mechanism that drives HspB1 to promote tumor progression and metastasis is still not well understood, several different HspB1 clients have already been identified that participate in the achievement of these particular endeaviors." (PMID 24514166, 2014). "Also, these data suggest that full-length HSPB1 protein requires proteolytic degradation to release the C-terminal fragment in order to endogenously inhibit tumor progression by regulating VEGF-induced ECs activation." (PMID 24465581, 2014). "Hence, the interactions of β-catenin with HspB1 appears to play a key role in the molecular pathways that influence tumor cell survival." (PMID 24514166, 2014). "Taken together, our results suggest that HSPB1 is mainly cleaved by MMP9 during tumor progression." (PMID 24465581, 2014). "We suggest that the inhibitory function of secretory wild-type HSPB1 may be depend on tumor cell types, but C-terminal HSPB1 have the inhibitory function consistently." (PMID 24465581, 2014).
tumor (continued). "For example, HspB1 can indirectly modulate extracellular matrix organization through the stimulation of metalloproteinase type 2, an enzyme that efficiently digests the matrix surrounding tumor masses." (PMID 24278676, 2012). "In neoplasias, HSPB1 is induced by cellular stress to protect cells against apoptosis." (PMID 22860099, 2012). "Despite the fact that the genes Xist and Hspb1 were found deregulated earlier in the process of malignant transformation of melan-a melanocytes, studies have shown they are likely to have distinct functional roles in the tumor progression." (PMID 22984562, 2012). "Also, IHC staining of 4-HNE confirmed that DOX enhanced lipid peroxidation in tumor tissue, while HSPB1 could significantly suppress it." (PMID 37454220, 2023). "HSPB1 may be involved in the regulation of the immune system in tumour initiation and progression." (PMID 37241117, 2023). "Moreover, we investigated whether restoring HSPB1 expression could reverse the tumor growth trend in vivo." (PMID 38041016, 2023). "Importantly, HSPB1 knockdown resulted in a higher tumor inhibition effect." (PMID 34922551, 2021). "In addition to these, the molecular chaperons showed contrast expressions such as heat shock protein 70 (HSP 70) identified with higher expressions, and heat shock protein beta 1 (HSPB1) showed reduced expressions in the GCT-untreated/control group indicating tumor recurrence." (PMID 33207819, 2020). "Notably, the proliferation experiment showed that overexpressing HSPB1 or increasing the O-GlcNAcylation of HSPB1 alone increased cell proliferation, whereas advanced O-GlcNAcylation of HSPB1 displayed a superior ability for cell multiplication in tumor progression." (PMID 31637018, 2019). "However, the role of HspB1 towards STAT3 is probably more complex than it has been originally thought since, depending upon the mutational background of the tumor, STAT3 can either be pro-oncogenic or have a tumor suppressor activity." (PMID 24514166, 2014). "Hence, depending on the tumor, the relation between HspB1 and STAT3 may have different consequences." (PMID 24514166, 2014). "In addition, many studies have shown that HSPB1 is upregulated in tumor tissues." (PMID 24465581, 2014). "Finally, HspB1 and HspB5 have been described to promote tumor progression, EMT and metastasis." (PMID 24514166, 2014). "Moreover, in vivo head and neck tumor xenograft studies revealed that aptamers could reduce tumor growth more efficiently than HspB1 depletion." (PMID 24514166, 2014). "Also, intact HSPB1 was more detected on tumor endothelium of MMP9 null mice than wild type mice." (PMID 24465581, 2014). "In addition, the tumor cells are particularly enriched in the small HSP Hsp27 (hspB1 gene product)." (PMID 23056925, 2012). "In tumor, this may lead in the degradation of HspB1 tumorigenic and metastatic client proteins." (PMID 24278676, 2012). "Stress-related genes, HSPB1 and BAG3, were expressed at higher levels in both tumor and paracarcinoma tissues in the NMPR_Pre-NAIC group compared to the MPR_Pre-NAIC group." (PMID 40295492, 2025). "Three genes, HSPB1, HPRT1, and GFPT1, were found to be significantly upregulated in tumor samples compared to normal samples." (PMID 38875364, 2024). "Compared with normal samples, the expressions of HSPA1A, HSPB1 and SERPINA1 were down-regulated in tumor samples, while TIMP1 was up-regulated in tumor samples." (PMID 39115879, 2024). "Given the pathogenic roles of MSI2 in tumor progression, as well as the protective roles of HSPs in ferroptosis, we demonstrated that MSI2 could regulate multiple HSPs to repress ferroptosis, especially the ferroptosis suppressor genes HSPB1 and HSPA5, as evidenced by previous studies." (PMID 38041016, 2023).
tumor (continued). "Validation using Western blotting analysis on 13 patients with type I EC at tumour stage 1 and 13 endometria samples confirmed the altered abundance of HBB, CKB, LDHB, and HSPB1." (PMID 37569364, 2023). "The upregulated expression of HSPB1 induced downregulation of ANKHD1-BP3 and promoted tumor metastasis." (PMID 36171217, 2022). "The angiogenesis cluster—besides containing some of the same previous ECM proteins—comprised the angiopoietin ANGPTL4 and other genes that are known to act in tumour-induced angiogenesis (AQP1, RAMP1, HSPB1, MYLK), for a total of 21 entries." (PMID 34439343, 2021). "HSPB1 and KRT18 were the tumor marker genes investigated, and patients were classified into PD-L1low and PD-L1high groups based on the relative expression of CD274 (Cutoff = 0.003)." (PMID 33754038, 2021). "The established activities of DYPS, MAL, and TIG1 are consistent with tumor suppression while CCND2, HSPB1 and PITX2 are mainly oncogenic." (PMID 27708246, 2016). "The results based on t test indicate that COL4A2, HSPB1, ITGB3, and MAP1A were significantly less expressed in tumor adjacent stroma in comparison with normal stroma (p values < 0.05)." (PMID 26158290, 2015). "In validation by real-time PCR, four genes (COL4A2, HSPB1, ITGB3, and MAP1A) demonstrated significantly lower expression in tumor-adjacent stroma compared to normal stroma (p value ≤ 0.05)." (PMID 26158290, 2015). "We also identified abundant expression of proteins involved in angiogenesis (ANXA2, CA2, ATP5B and HSPB1) in MDCKYBX1 tumours." (PMID 25980435, 2015). "Four genes (COL4A2, HSPB1, ITGB3, and MAP1A) were significantly less expressed in tumor adjacent stroma in comparison with normal stroma (p values < 0.05)." (PMID 26158290, 2015). "We are currently studying the effects of HSPB1 glycosylation, phosphorylation and dimerization on MMP9-induced HSPB1 cleavage during tumor progression." (PMID 24465581, 2014). "To confirm HSPB1 cleavage by MMP9 during tumor progression, we generated B6F10 cell lines secreting wild-type HSPB1 (consisting of a Flag-tagged N-terminus and a Myc-tagged C-terminus)." (PMID 24465581, 2014). "As shown inFigure 6, wild type and C-terminal fragment of HSPB1 were mainly detected in tumor endothelium during tumor progression, suggesting that secreted and cleaved HSPB1 targeting tumor endothelium may play an important role in the regulation of tumor angiogenesis." (PMID 24465581, 2014). "Thus, we investigated whether HSPB1 fragments could be detected in tumor metastases." (PMID 24465581, 2014). "However, the data showing that TNBC-TICs exhibit classical signs of aggressive phenotype shown by human TNBC including increased tumor growth and enhanced metastatic potential, led us to hypothesize that the differential expression of mouse HspB1 and Hsp72/HspA1A, might be a possible explanation." (PMID 22452810, 2012). "However, tumors that express Hsp72/HspA1A on their plasma surface are sensitive to anti-tumor effector cells, which indicate increased surface expression of Hsp72/HspA1A on tumors and down regulation of human HspB1 expression could inhibit tumor growth and eliminate metastasis." (PMID 22452810, 2012). "COPS5, which is overexpressed in HCC in an amplification‐ and ATF4‐dependent manner, stabilizes MK2 through deubiquitination and, in turn, induces HSPB1 activation, protecting HCC cells from ferroptosis and thus promoting sorafenib resistance and tumor progression." (PMID 40198582, 2025). "HSPB1, a subtype of the small HSP family, is involved in multiple biological processes containing macrophage infiltration, tumor proliferation and metastasis, mitochondrial dysfunction, epithelial-mesenchymal transition, as well as endoplasmic reticulum stress." (PMID 38429742, 2024). "Analysis of IHC staining results for MSI2, HSPB1, p-HSPB1(Ser78) and Ki67 showed that MSI2 knockout could reduce the expression of HSPB1, p-HSPB1(Ser78) and the tumor proliferation capacity in transgenic CAC mice." (PMID 38041016, 2023).
tumor (continued). "Cluster 1 comprises genes important for skeletal muscle (ACTA1) and muscle function (ACTN1) and includes a crucial gene (AKT1) known to regulate insulin signaling, cell survival, and tumor progression, as well as two chaperones: HSPA1A and HSPB1 (heat shock proteins (HSPs))." (PMID 36767649, 2023). "HSPB1, EGFR, and TYK2 were highly expressed in tumor tissue in the Human Protein Atlas database." (PMID 36171217, 2022). "SPDEF, TRIM3, HSPB1, SPINT1, EPN3, and LRFN2 were significantly highly expressed in the HER2-positive type than in TNBC (p < 0.05), as the HER2-positive type is reported to have a larger tumor size and higher stage." (PMID 36428562, 2022). "Furthermore, the expression levels of AS-tDR-007333, HSPB1, ELK4, and MED29 in xenograft tumor tissues were significantly suppressed in the AS-tDR-007333-inhibitor group compared with that of NC and control groups." (PMID 35526007, 2022). "In addition, the highly phosphorylation (e.g., HSPB1 S82, KRT14, KRT13 S427, etc.)were both detected in tumor tissues and their paired normal tissues in EESCC." (PMID 35397555, 2022). "Genes ASPH, HSPB1, SQSTM1, ANXA2, and GSN (Cluster A) and PURA and MX1 (Cluster B) were downregulated for both datasets in PCa tissue vs. normal gland or normal adjacent to tumor tissue." (PMID 32640729, 2020). "In addition, it has been proposed that the dysregulations of HSPB1, ALDOB, and RPL30 are sufficient to trigger tumor progression." (PMID 30344796, 2018). "HSF1 and HSPB1 inhibition increases the concentrations of iron and ROS in cells, ultimately suppressing the growth of tumour cells, whereas PKC‐regulated HSPB1 phosphorylation can prevent cell ferroptosis because phosphorylated HSPB1 inhibits the uptake of iron and lipid ROS by cells." (PMID 27860262, 2017). "Interestingly, we observed the abundant expression in the tumours of several proteins known to be involved in angiogenesis, including ANXA2, CA2, ATP5B and HSPB1." (PMID 25980435, 2015). "In addition, we found that in PMA-treated U937 cells, HSPB1 cleavage occurred depending on MMP9, suggesting that in tumor microenvironment, macrophages play a role in MMP9-induced HSPB1 cleavage." (PMID 24465581, 2014). "Furthermore, HSPB1 cleavage by MMP9 occurred during tumor progression and the anti-angiogenic HSPB1 fragment inhibited intratumoral MVD and tumor growth." (PMID 24465581, 2014). "Because the C-terminal HSPB1 fragment inhibits VEGF-mediated angiogenesis, we hypothesized that HSPB1 cleavage inhibits VEGF-regulated tumor progression in vivo." (PMID 24465581, 2014). "Here, we suggest that HSPB1 is primarily secreted from tumor endothelial cells, not tumor cells and cleavage of soluble HSPB1 by MMP9 leads to endogenous anti-angiogenic effects during tumor progression." (PMID 24465581, 2014). "Moreover, HSPB1 wild-type or fragments secreted by B16F10 stable cell lines were detected significantly in tumor endothelia, suggesting that soluble HSPB1 targets tumor vascular endothelium and regulates tumor vasculature." (PMID 24465581, 2014). "On the negative side, high levels of HspB1 cell surface expression correlates with tumor growth and ability to metastasize." (PMID 24278676, 2012). "Furthermore, high HSPB1 expression may have triggered EMT-related genes (SNAI1, SNAI2, SOX10), suggesting a complex dual effect of 2S-13 on tumor plasticity." (PMID 41007338, 2025). "Variations within genes of the MAPK signaling pathway in TECs, such as amplifications in CDC42, HSPB1, NRAS, and deletions in AKT1, MAPK1, might reveal their significance in HCC, possibly related to their roles in tumor growth and progression, particularly in signaling pathways." (PMID 39484208, 2024). "Interestingly, cleavage of HSPB1 was detected only in conditioned media from tumor vascular ECs, but not from tumor cells." (PMID 24465581, 2014).